EGFR (epidermal growth factor receptor)
Diseases named in the same sentence as EGFR in open-access papers (continued):
Sharing a sentence is not in itself a finding about the gene and the disease.
cancer (continued). "Epidermal growth factor receptor (EGFR) activation events and the mammalian target of rampamycin (mTOR) are considered important therapeutic targets in alleviating cancer conditions." (PMID 29234489, 2017). "Treatment of cancer cells with chemotherapy drugs induces the expression of MUC1, which stimulates the activation and nuclear distribution of EGFR." (PMID 28796259, 2017). "ALDH+ cells are considered representative of cancer stem-like cells and are reported to be a consequence of crosstalk between EGFR and NOTCH signaling pathways in EGFR mutant tumors." (PMID 28521301, 2017). "Due to the robust preclinical data, there is significant interest in using the irreversible EGFR/HER2 inhibitors neratinib and afatinib to treat HER2-mutant cancers." (PMID 29371993, 2017). "We observed higher Endo II levels in TNBC and HER2+ cancer cell lines, including SK-BR-3 and HCC1954 cells, which co-expressed EGFR and HER2." (PMID 28974266, 2017). "Over the last decade, two of the HER family members, HER1/EGFR and HER2, have been researched extensively in the context of various types of cancer." (PMID 28210516, 2017). "Apart from chemically synthesized compounds such as gefitinib or erlotinib, the metabolite butein, found in the stembark of cashews, was found to efficiently inhibit c-Met and EGFR and induce apoptosis in TKI-resistant cancer cells." (PMID 28417948, 2017). "To this end we focused on CRC, a cancer in which oncogenic KRAS is well established to be a central driver of primary and acquired resistance to anti-EGFR therapies." (PMID 28593995, 2017). "Among different types of EGFR dimers, EGFR-HER2 and HER2-HER3 are well known in different types of cancers." (PMID 29088782, 2017). "Highly expressed mRNA of EGFR was detected in more than 90% of histologically normal mucosa and cancerous parts excised from HNSCC patients compared with control samples from non-cancer patients." (PMID 28740192, 2017). "Co-inhibition of EGFR and AKT phosphorylation by VJ can reverse the chemoresistant fate of platinum resistant cancer cases, but needs further investigation." (PMID 29234489, 2017). "Anti-EGFR-GNs suppressed the growth of MDA-MB-468 cells and exhibited similar anti-cancer efficacies observed in MDA-MB-231 cells." (PMID 29156817, 2017). "The ErbB receptor family, including epidermal growth factor receptor (ERBB1/EGFR), represents a group of receptor tyrosine kinases (RTKs) with established roles in cancer." (PMID 28550306, 2017). "In human cancer tissue, the expression of FOXD3 was reduced, however, the EGFR/Ras/Raf/MEK/ERK pathway was activated." (PMID 27926503, 2017). "Other researchers have shown that overexpression of ciRS-7 in cancer tissues permitted inhibition of miR-7 and subsequent activation of EGFR and RAF1 oncogenes, again, strengthening the argument that circRNAs play a role in cancer initiation and development." (PMID 28634583, 2017). "The primary molecular classification marker exhibited higher variability than other classification markers in two of the cancer cell lines (HER2: σSK-BR-32=2.08 × 1012, n=27, ER: σMCF72=1.24 × 1015, n=35; EGFR: σBT-202=3.15 × 1011, n=27)." (PMID 28332571, 2017). "In this review, we focus on the landscape of genomic alterations of EGFR, HER2, HER3 and HER4 in cancer and the clinical implications for patients harboring these alterations." (PMID 29371993, 2017). "Further, epidermal growth factor receptor I (EGFR)-binding peptides are genetically attached to the MBD1 of DMA_21mCG, enabling its efficient endocytosis into EGFR-overexpressing cancer cells." (PMID 29229979, 2017). "EGFR expression also promotes EMT-like transition and cancer cell survival with subsequent Twist, Snail, and Slug induction." (PMID 29038587, 2017). "Probably, constitutive EGFR activation in NSCLC cells leads to an increase of AREG signaling since the early disease stage, driving the cancer progression toward osteolytic bone metastasis." (PMID 28600504, 2017).
cancer (continued). "And angiogenesis causing up-regulated expression of the vascular endothelial growth factor (VEGF) on human cancer cells by it's ligands such as EGF and TGF-α can also be a factor to induce resistance to EGFR blocking agents." (PMID 28445134, 2017). "Despite a significant growth advantage for certain cancer cells in TCM, -E, -I media (MGH121-1 and MGH045-1), their response to EGFR or ALK inhibition was nearly identical to cells growing in R10 media." (PMID 29241554, 2017). "Here we determined the radio-sensitizing potential of a pan-EGFR inhibitor afatinib and explored the mechanism by which afatinib augmented radio-sensitivity in HNSCC cancer models in vitro and in vivo." (PMID 28423495, 2017). "Altogether, these data show that in EGFR‐addicted carcinoma cell lines, HSP27 silencing affected cell survival and allowed the EGFR inhibitor to exert a full cytotoxic effect." (PMID 28182330, 2017). "The most commonly mutated domain is the Tyrosine kinase domain observed in 20 different proteins, including such well-known cancer driver genes as ALK, EGFR or BRAF." (PMID 27150584, 2016). "Furthermore, impairment of the stress-induced EGFR endocytosis enhanced UV-irradiation or cisplatin-induced apoptosis, suggesting that the stress-induced endocytosis of EGFR might play a role in antagonizing the stress-induced apoptosis in cancer cells." (PMID 27034618, 2016). "This is in agreement with the understanding that EGFR stimulation leads to downstream activation of AKT, which in turn influences GSK330, 31 in normal and cancer cells." (PMID 27279498, 2016). "c-Cbl downregulates multiple RTKs including EGFR, MET, and others, which in turn regulate Wnt signaling in different cancer types (RTK-Wnt crosstalk)." (PMID 27661103, 2016). "Members of the human epidermal growth factor receptor (HER) family of receptor tyrosine kinases EGFR (HER1, ERBB1), HER2 (ERBB2), HER3 (ERBB3), and HER4 (ERBB4) are therapeutic targets in several cancers." (PMID 27610130, 2016). "Like EGFR, IGF-1R also plays a role in the maintenance of the oncogenic phenotype in various cancers and is known to mediate anti-apoptotic signals and cell proliferation." (PMID 27716204, 2016). "Each member of the epidermal growth factor receptor (EGFR) family plays a key role in normal development, homeostasis, and a variety of pathophysiological conditions, most notably in cancer." (PMID 27597943, 2016). "Among members of the epidermal growth factor receptor (HER, ErbB) family, HER-2 is the most potent oncogenic protein and positively correlates with the metastasis of cancer cells." (PMID 27391337, 2016). "FeDC-E NPs inhibited the EGFR–ERK–NF-κB signaling pathways, and subsequently suppressed the migration and invasion capabilities of the highly invasive and migrative CL1-5-F4 cancer cells." (PMID 27833124, 2016). "CRISPR/Cas9‐mediated editing will lead to HDR‐dependent insertion of a stop codon that terminates EGFR translation at exon 19 or 20, or an NHEJ‐dependent random insertion/deletion, destroying EGFR TK activity and cancer progression." (PMID 26747090, 2016). "Moreover, abnormalities in EGFR activation in the context of chronic diseases such as cancer or IBD may not only simply be due to altered expression of EGFR or its ligands but also be related to altered expression or activation of NOX enzymes that regulate this signaling pathway." (PMID 28101521, 2016). "In this study, we have identified for the first time a direct interaction between EGFR and Axl RTKs, with EGF/EGFR-induced activation of Axl as a novel signalling pathway to invasion in cancer cells." (PMID 27775700, 2016). "Other authors have demonstrated in various human cancer cells, including TNBC cell lines, that combination of cetuximab with gefitinib has a synergistic effect on cell proliferation and EGFR downstream signaling pathways." (PMID 27655662, 2016).
cancer (continued). "Data obtained under these experimental setting show that both EGFR and certain GPCR are co-overexpressed and simultaneous inhibition of both EGFR and GPCR leads to additive or synergistic growth inhibition in cancers." (PMID 26771606, 2016). "Along this line, both EGFR and HER3 have been suggested as prognostic markers in several types of cancer as well as drug targets, and also to be involved in drug resistance in e.g. breast, lung and ovarian cancers." (PMID 26844548, 2016). "The role of growth factors-driven signaling in the pathogenesis of human cancer has long been established for EGF, VEGF and their receptors EGFR and VEGFR." (PMID 27806094, 2016). "The top most influential components, such as EGFR, PI3K, ERK, and Ras, have been previously explored as drug targets in multiple cancer types." (PMID 26904540, 2016). "A similar mechanism of action has been observed for antibodies approved by FDA for cancer treatment, e.g. Trastuzumab (targets ERBB2), Cetuximab (targets EGFR), Rituximab (targets CD20) and Bexxar (targets CD20)." (PMID 27270318, 2016). "All these results indicate that both EGFR and GAC play crucial roles in regulating cancer cell function." (PMID 26575584, 2016). "EGFR epidermal growth factor receptor, also known as ErbB1, was the first RTK to be discovered, and it has played an important role in connecting RTKs to cancer." (PMID 27486382, 2016). "Cancer cells not only release EGF, but they also overexpress the EGF receptor (EGFR), which is recognized as the initial, indispensable molecular alteration in pancreatic carcinogenesis." (PMID 27655713, 2016). "Like EGFR, IGF-1R is involved in normal cellular growth as well as transformation and progression of malignancy in various cancers." (PMID 27716204, 2016). "Studies in microfluidic channels have contributed to the discovery of genes required for cancer cell migration and identification of proteins, such as EGFR or CXCL12, that act as chemoattractants for cancer cells." (PMID 26904541, 2016). "STAT3 is also activated by RTKs, such as the epidermal growth factor receptor (EGFR) and VEGFR, cytoplasmic kinases, such as Src, as well as some cancer therapies, such as ionizing radiation (IR)." (PMID 27148255, 2016). "The inhibitors of Wnt, EGFR, p38 MAPK, Hedgehog and NF-κB reduced the total protein expression level and the surface expression level of JAM-A in the cancer cells." (PMID 27036044, 2016). "Overexpressed EGFR is not only regarded as a driving event for NSCLC, but also a promising biomarker for antibody-based cancer treatments." (PMID 26988752, 2016). "Through the specific targeting using the EGFR antibody CET to the channels of MP-SiO2 NP, we have established a nano-medicine specifically targeting cancer cells with high EGFR expression." (PMID 27151505, 2016). "EGFR and notch are both involved in regulation of GBM cancer cells by promoting their survival, therapeutic resistance and pro-angiogenic signaling." (PMID 27118928, 2016). "We also show that Anti-EGFR mAbs can modulate SOCE and cancer cell migration through the Akt pathway." (PMID 27102434, 2016). "The widespread occurrence of this signaling mechanism has been verified in many cancer cell types, for example, HB-EGF shedding and subsequent EGFR transactivation is mediated by ADAM10 and ADAM17 in lung carcinoma cells." (PMID 27187360, 2016). "Many tyrosine kinase inhibitors and monoclonal antibodies against EGFR and ERBB2 RTK have successfully been used as cancer drugs, for example cetuximab and panitumumab for EGFR overexpression, and afatinib and dacomitinib as pan-HER inhibitors." (PMID 26907936, 2016). "The four members of the epidermal growth factor receptor (EGFR/ERBB) family form homo- and heterodimers which mediate ligand-specific regulation of many key cellular processes in normal and cancer tissues." (PMID 26745281, 2016).
cancer (continued). "However, our previous study demonstrated that EGFR amplification might be the fundamental cause for varied EGFR-TKI response rather than the cancer cell proportion." (PMID 27418143, 2016). "These clusters are enriched in cancer-related pathways, such as BCR signalling, epidermal growth factor receptor (EGFR) signalling and extracellular signal-regulated kinase (ERK) signalling." (PMID 27982015, 2016). "For instance, ligation of EGFR by EGF induces endogenous production of intracellular reactive oxygen species (ROS) and H2O2 in cancer cell lines." (PMID 27199982, 2016). "Immune responses to HER2, another molecule of the ErbB/HER onocogene family, have been well studied, but only limited information on the immune responses to EGFR in cancer has been currently available." (PMID 27833557, 2016). "NRP-1 interacts with EGFR and promotes its signaling cascade elicited upon EGF stimulation in cancer cells." (PMID 26795388, 2016). "In the context of cancer treatment, such a device could efficiently detect specific genetic mutations that are known to respond well to particular therapies (e.g., KRAS, HER2, EGFR, etc.), resulting in improved drug efficacy and an optimized-for-the-individual approach to treatment." (PMID 27149679, 2016). "Both types of HLG1 dimers showed very similar inhibitory effects on cancer cell viability, indicating that preparation from ICS fraction is an ideal strategy for producing anti‐EGFR h528 scFv multimers at high yields." (PMID 27419062, 2016). "Conversely, the GSr-like signature is characterized by a strong activation of downstream targets of the EGFR and PI3K/mTOR pathway, which plays a critical role in cancer and, in particular, in GBM43." (PMID 26857460, 2016). "Taken together, our data indicate thatquercetin is an effective anti-cancer agent against MMP-2- and MMP-9-mediatedmetastasis in EGFR-overexpressing HNSCC." (PMID 27510965, 2016). "Other oncogenes first identified in retroviruses and later as drivers in human cancer include myc, raf, erbB1 (EGFR: Epidermal growth factor receptor), AKT, and sis (PDGF: platelet derived growth factor, subunit B)." (PMID 27102293, 2016). "Molecular target anticancer drugs such as EGFR-tyrosine kinase inhibitors (TKIs) and ALK inhibitors have dramatically changed the strategy of clinical treatment of cancer." (PMID 27070423, 2016). "The epidermal growth factor receptor (EGFR) plays an important role in tumorigenesis and maintenance of cancers, making it a possible therapeutic target for cancer treatment." (PMID 27016412, 2016). "CUDC-101 is a dual inhibitor of EGFR, HER2, and HDACs, and displays potent antiproliferative and proapoptotic activities against cancer cells." (PMID 26934320, 2016). "X66 effectively decreased the levels of specific oncogenic proteins, such as HER2, EGFR and BCR-ABL in BT-474, A549 and K562 cancer cell lines." (PMID 27105490, 2016). "EGFR, VEGF, bcl-2 and survivin were expressed in the eight cancer cell lines, and siSp1,3,4 downregulated these gene products; however, the effects of siSp1, siSp3 and siSp4 were variable and there were also gene- and cell context-specific differences." (PMID 26967243, 2016). "Drp1 driven mitochondrial fission can be activated by various cancer signaling pathways involving PKA, AMPK and EGFR-Ras." (PMID 27509055, 2016). "Together, these results support our initial finding that that EGFR, ERBB3 and CDKN1B expression predict differential dependence on PI3K/AKT and MAPK signaling in HER2+ cancer cells." (PMID 27035903, 2016). "The younger age group was significantly more likely to have wild-type EGFR (OR = 1.68, 95% CI: 1.30∼2.17, P < 0.001), and stage IIIB/IV cancer at diagnosis than the older group (OR = 1.84, 95% CI: 1.22∼2.76, P = 0.003)." (PMID 27191886, 2016).
cancer (continued). "Recently, it was reported that an LM5 fragment binds to the epidermal growth factor receptor and stimulates MMP-2 expression and cell migration as a possible mechanism leading to cancer invasion into the stroma." (PMID 27404587, 2016). "Interestingly, several of the proteins that exhibited alterations in N-glycoprotein expression levels (e.g., EGFR (epidermal growth factor receptor), LGALS3BP (Galectin-3-binding protein) and PLOD3 (Procollagen-lysine, 2-oxoglutarate 5-dioxygenase 3)) in hiPSCs are linked with cancer." (PMID 27808266, 2016). "Autophosphorylation of EGFR on specific tyrosine residues activates PI3K/AKT, Ras/MAPK, and JAK/STAT signaling pathways that lead to cancer cell survival." (PMID 27256981, 2016). "Among the biomarker gene pairs, PPP1R13L, EGFR, IL15RA, or PIM1 are acting in the cancer core pathways." (PMID 26916442, 2016). "Restoration of mature miR-206 inhibited cancer cell proliferation, migration, and invasion in human lung SCC cell lines through down-regulation of both mRNA and protein levels of MET and EGFR." (PMID 26646588, 2016). "We tested combinations of the EGFR/ERBB2 inhibitor neratinib with the cell cycle inhibitors (BI-2536, GSK-1070916 and paclitaxel or docetaxel) in the MYC-amplified cancer cell line NCI-H82." (PMID 26018524, 2015). "Afatinib is the first irreversible multi-targeted TKI, functioning by selectively inhibiting EGFR and HER-2 and thereby attenuating the downstream oncogenic signaling pathways correlated with cancer proliferation, invasion, metastasis and angiogenesis." (PMID 26317651, 2015). "EGFR, HER2, and HER3 contribute to the initiation and progression of human cancers, and are therapeutic targets for monoclonal antibodies and tyrosine kinase inhibitors." (PMID 25865227, 2015). "Previous studies have shown that the oncogenic activity of cancer-derived CTED2, CTED5 and CTED8 mutants was effectively suppressed by the EGFR inhibitors erlotinib or cetuximab both in vitro and in vivo." (PMID 25826094, 2015). "This is different from other reported third generation EGFR inhibitors (WZ4002, CO1686 and AZD9291) that can significantly affect the phosphorylation of AktS473 in L858R and del 19 mutant cancer cell lines." (PMID 26375053, 2015). "Epidermal growth factor receptor (EGFR), a transmembrane tyrosine kinase receptor, plays important roles in various cancers." (PMID 26436086, 2015). "Liver rebiopsy on progression identified an afatinib-resistant cancer with combined SCLC and NSCLC within neuroendocrine morphology, retaining the EGFR exon-19 deletion." (PMID 25699082, 2015). "EGFR is a member of the HER family, which is particularly highly expressed in malignant tumors with epithelial tissue sources." (PMID 26579537, 2015). "However, it is also likely that immunohistochemical evaluation of the EGFR protein expression may not be sufficiently accurate to detect the loss of EGFR protein in cancer tissue, thus compromising data analysis and interpretation." (PMID 25663927, 2015). "Epithelial to mesenchymal transition (EMT), a process in which cancer cells lose cell-to-cell adhesion and gain invasive properties, has been described in preclinical models, including SCCHN, as a possible mechanism of EGFR therapy resistance." (PMID 26437222, 2015). "Although the reason for high expression of ANO1 in tumors is unclear, several studies have shown that ANO1 is involved in oncogenic signaling by activating EGFR and CAMK pathways to promote cell cycle and cancer progression." (PMID 26305547, 2015). "Cytotoxic anticancer drugs inhibit DNA replication or mitosis resulting in apoptosis in several types of cancers including NSCLC, while EGFR-TKI inactivates EGFR signalling in NSCLC cells." (PMID 26439264, 2015). "Key players in cancer development and growth, HER2 and EGFR have emerged as attractive targets for pharmacological intervention." (PMID 26143491, 2015).